ABCA12 (ATP binding cassette subfamily A member 12)
Description:
Transports lipids such as glucosylceramides from the outer to the inner leaflet of lamellar granules (LGs) membrane, whereby the lipids are finally transported to the keratinocyte periphery via the trans-Golgi network and LGs and released to the apical surface of the granular keratinocytes to form lipid lamellae in the stratum corneum of the epidermis, which is essential for skin barrier function. In the meantime, participates in the transport of the lamellar granules-associated proteolytic enzymes, in turn regulates desquamation and keratinocyte differentiation. Furthermore, is essential for the regulation of cellular cholesterol homeostasis by regulating ABCA1-dependent cholesterol efflux from macrophages through interaction with NR1H2 and ABCA1 (By similarity). Plays pleiotropic roles in regulating glucose stimulated insulin secretion from beta cells, regulating the morphology and fusion of insulin granules, lipid raft abundance and the actin cytoskeleton (By similarity). Also involved in lung surfactant biogenesis (By similarity).
Synonyms: DKFZP434G232; LI2; ARCI4A; ARCI4B; ICR2B
Tractability: Small molecule: it belongs to a druggable protein family. Antibody: its Gene Ontology location is reachable by antibodies, with high confidence; UniProt predicts a signal peptide or a membrane-spanning region; the Human Protein Atlas places it where antibodies can reach.
Gene: Protein-coding gene on chromosome 2 (214,931,542 to 215,138,626, reverse strand). Ensembl gene ENSG00000144452.
Subcellular location: Cytoplasmic vesicle, secretory vesicle membrane; Golgi apparatus membrane
Subcellular location (Human Protein Atlas): Plasma membrane; Vesicles; Cytosol; Nucleoli
Pathways (Reactome):
Disease: Defective ABCA12 causes ARCI4B
Transport of small molecules: ABC transporters in lipid homeostasis
Gene Ontology:
Molecular function: apolipoprotein A-I receptor binding; ATPase-coupled intramembrane lipid transporter activity; lipid transporter activity; protein binding; signaling receptor binding; ATP binding; ATPase-coupled lipid transmembrane transporter activity; ATPase-coupled transmembrane transporter activity; ABC-type transporter activity; ATP hydrolysis activity
Biological process: ceramide metabolic process; ceramide transport; corneocyte desquamation; intracellular protein transport; lipid transport; phospholipid efflux; positive regulation of cholesterol efflux; protein localization to plasma membrane; regulated exocytosis; regulation of keratinocyte differentiation; secretion by cell; cellular homeostasis; establishment of skin barrier; positive regulation of intracellular lipid transport; regulation of insulin secretion involved in cellular response to glucose stimulus; skin morphogenesis; lipid translocation; positive regulation of cholesterol transport; transmembrane transport
Cellular component: cytoplasm; epidermal lamellar body; epidermal lamellar body membrane; Golgi membrane; plasma membrane; membrane; cytosol; secretory granule membrane; transport vesicle membrane
Genetic constraint (gnomAD): Loss-of-function variants: 150 observed, 294.89 expected, observed/expected ratio (o/e) 0.51, 90% interval 0.44 to 0.58. The upper end of that interval is the gene's LOEUF score, 0.58, which puts it in group 2 of 6, group 1 being the genes least tolerant of losing a copy. Missense variants: 2,773 observed, 3,228.1 expected, observed/expected ratio (o/e) 0.86, 90% interval 0.83 to 0.89. Synonymous variants: 1,054 observed, 1,165.8 expected, observed/expected ratio (o/e) 0.9, 90% interval 0.86 to 0.95.
Homologues: Orthologues: chimpanzee ABCA12 (99% identical), macaque ABCA12 (98% identical), dog ABCA12 (91% identical), rabbit ABCA12 (91% identical), pig ABCA12 (91% identical), mouse Abca12 (90% identical), rat Abca12 (89% identical), guinea pig ABCA12 (89% identical), tropical clawed frog abca12 (47% identical), zebrafish abca12 (37% identical), Caenorhabditis elegans abt-2 (21% identical), Caenorhabditis elegans abt-4 (19% identical), and 10 more. Paralogues in human: ABCA13 (36% identical), ABCA1 (28% identical), ABCA4 (27% identical), ABCA2 (26% identical), ABCA7 (26% identical), ABCA3 (20% identical), ABCA5 (16% identical), ABCA8 (15% identical), ABCA6 (15% identical), ABCA9 (15% identical), ABCA10 (15% identical).
Diseases named in the same sentence as ABCA12 in open-access papers:
ABCA12 is named in the same sentence as 78 diseases in open-access papers, as found by Europe PMC text mining. Sharing a sentence is not in itself a finding about the gene and the disease. The quoted sentences say what the papers report.
Harlequin ichthyosis (38 papers, 2008 to 2025). Harlequin ichthyosis (HI) is the most severe variant of autosomal recessive congenital ichthyosis (ARCI; see this term). "Harlequin Ichthyosis (HI), a rare genetic disease caused by mutations in the ABCA12 gene, is the most severe form of autosomal recessive congenital ichthyosis." (PMID 41376622, 2025). "Genetic testing for ABCA12 was performed on day 9 of life, with written informed consent from the parents, and identified a homozygous pathogenic variant c.179G>C, p.(Arg60Pro) in the ABCA12 gene, confirming the diagnosis of Harlequin ichthyosis." (PMID 41458703, 2025). "Recent studies have identified multiple novel ABCA12 mutations and described genotype-phenotype correlations within the spectrum of autosomal recessive congenital ichthyosis, including Harlequin ichthyosis." (PMID 41458703, 2025). "In the ABCA12 gene, the type of mutation determines the phenotype: truncating variants lead to harlequin ichthyosis, whereas missense variants lead to congenital ichthyosiform erythroderma or lamellar ichthyosis." (PMID 38540347, 2024). "Within the spectrum of ARCI, mutations in the ABCA12 gene are notably associated with more severe phenotypes, including harlequin ichthyosis and congenital ichthyosiform erythroderma." (PMID 39748812, 2024). "It mainly appears in three forms: lamellar ichthyosis, congenital ichthyosiform erythroderma, and the most severe, harlequin ichthyosis, linked to ABCA12 gene mutations." (PMID 39748812, 2024). "Despite of the clinical presentation, we demonstrated that the affected patients were genetically double heterozygous for two different mutations in the ABCA12 gene, known to be responsible for harlequin ichthyosis." (PMID 37762265, 2023). "Harlequin ichthyosis (HI) is a rare skin disorder with extremely high lethality due to a mutation of the ABCA12 gene." (PMID 37355352, 2023). "The mutations are located in exon 30 and exon 31 of the ABCA12 gene, the major gene associated with harlequin ichthyosis." (PMID 37762265, 2023). "Truncating mutations in the ATP-binding cassette subfamily A member 12 (ABCA12) gene tend to cause Harlequin ichthyosis (HI, OMIM #242500), while ABCA12 missense mutations are associated with lamellar ichthyosis (LI; OMIM #601277)." (PMID 35269649, 2022). "The most severe subtype of ARCI is Harlequin ichthyosis (HI), which is triggered by inactivating mutations of the ABCA12 gene." (PMID 34199106, 2021). "Harlequin Ichthyosis (HI) is a severe genetic disorder of skin keratinization, caused by mutations in the ABCA12 gene, inherited as autosomal recessive trait." (PMID 32293521, 2020). "The three types of autosomal recessive congenital ichthyoses, including harlequin ichthyosis, lamellar ichthyosis and congenital ichthyosiform erythroderma are caused by a mutation in the ATP-binding cassette transporter A12 (ABCA12) gene." (PMID 26786937, 2016). "The human cultured keratinocytes obtained from patients with harlequin ichthyosis carrying a mutation of ABCA12 showed glucosylceramide accumulated around the nuclei, unable to reach the external regions of the cytoplasm." (PMID 26786937, 2016). "ABCA12, a gene with function in keratinocyte lamellar body lipid transportation and its loss-of-function mutations are associated with harlequin ichthyosis, was also significantly reduced in FOXC1-silenced KC." (PMID 27907090, 2016). "Harlequin Ichthyosis is a severe skin disease caused by mutations in the human gene encoding ABCA12." (PMID 27551807, 2016). "Harlequin Ichthyosis (HI) is a severe and often lethal hyperkeratotic skin disease caused by mutations in the ABCA12 transport protein." (PMID 18802465, 2008). "The primary cargo glucosylceramide is transported to the maturing LBs by the ABC transporter ABCA12 localized on its limiting membrane, and accordingly, the loss of function mutations of ABCA12 blocks LB biogenesis/maturation, resulting in the fatal condition Harlequin ichthyosis." (PMID 40552305, 2025).
Harlequin ichthyosis (continued). "The most severe form of ARCI, harlequin ichthyosis, is caused by mutations in ABCA12." (PMID 36980989, 2023). "This case report confirms that mutations in the ABCA12 gene could not only cause the rare skin condition called harlequin ichthyosis, but they might also lead to a phenotype that is attributable clinically to the much less severe EKVP disease." (PMID 37762265, 2023). "Interestingly, some of these genes, i.e. KRT1, KRT9, KRT16, DSG1, DSC2 and JUP, are mutated in hereditary PPKs, while the ABCA12 gene is defective in harlequin ichthyosis characterized by the loss of the skin lipid barrier." (PMID 35854363, 2022). "Comparison to previously reported cases was consistent with the hypothesis that severe loss of function ABCA12 mutations are associated with Harlequin Ichthyosis and missense mutations are preferentially associated with milder phenotypes." (PMID 24278723, 2012). "Harlequin ichthyosis (HI), a rare autosomal recessive genetic disorder caused by mutations in the ABCA12 gene, represents the most severe form of congenital ichthyosis." (PMID 39882557, 2025). "Harlequin ichthyosis (HI) is a genetic disorder caused by ABCA12 gene mutations, presenting with thick, scaly skin and deep fissures." (PMID 40667495, 2025). "The discovery that ABCA12 gene mutations are associated with the skin disease harlequin ichthyosis (HI) is an example of where SNP microarray technology was used successfully to elucidate the genetic locus associated with this disease." (PMID 25093584, 2014). "Mutations in the ABCA12 gene have been identified as the cause of autosomal recessive congenital ichthyosis (ARCI), including Harlequin Ichthyosis, congenital ichthyosiform erythroderma, and lamellar ichthyosis, depending on the type of ABCA12 mutation." (PMID 40698039, 2025). "Harlequin ichthyosis (HI) is a genetically inherited epidermal disorder due to the mutation of the ABCA12 gene, which is responsible for lipid transportation, and presents with large keratinised scales characterised by deep erythematous fissures, with ectropion and eclabium." (PMID 38250222, 2024). "Mutations in these genes lead to human genetic skin diseases such as epidermolytic hyperkeratosis (KRT1), ichthyosis vulgaris (FLG), seborrheic dermatitis (ZNF750), psoriasis (LCE3D), and harlequin ichthyosis (ABCA12)." (PMID 34543262, 2021). "Harlequin ichthyosis (HI) is the most severe form of ARCI and is caused by a mutation of the ATP-binding cassette A12 gene (ABCA12)." (PMID 33652877, 2021). "In an Abca12 pig model of Harlequin ichthyosis, acitretin treatment resulted in a redistribution of ABCA12 in the skin compared to wild-type pigs, and thus, a higher survival rate." (PMID 34977908, 2021). "In this report we have used a forward genetic approach to identify a model of harlequin ichthyosis which has allowed us to characterise Abca12's function as a key regulator of lipid homeostasis and cholesterol transport." (PMID 18802465, 2008). "ABCA12 mediates lipid transporter activity, signals receptor binding, and has active trans-membrane transporter activity identified that ABCA12 is the major gene that influences Harlequin Ichthyosis in humans and later was identified in livestock species." (PMID 37620802, 2023). "The ABCA transporter family is involved in the transport of a variety of lipid substrates, some of them being associated with severe recessive human inherited disorders such as Tangier disease (ABCA1), Stargardt disease (ABCA4) or harlequin ichthyosis (ABCA12)." (PMID 34638622, 2021). "The biology of harlequin ichthyosis (HI), a devastating skin disorder caused by loss-of-function mutations in the gene ABCA12, is poorly understood, and to date, no satisfactory treatment has been developed." (PMID 32544098, 2020).
Harlequin ichthyosis (continued). "A defective ABCA12 results in a reduced lipid content in LB, as well as an abnormal LB morphology, a reduced pool of LB organelles, an impaired secretion into the extracellular space and a compromised barrier function that can be very severe in Harlequin Ichthyosis." (PMID 40698039, 2025). "Among them, mutations in ABCA12, a member of the ABC transporter superfamily, cause Harlequin ichthyosis (HI), a disorder that presents at birth with a thick, tight skin that is susceptible to cracking." (PMID 23226340, 2012).
ichthyosis (32 papers, 2008 to 2026). Disorders of cornification that are characterized by visible scaling and/or hyperkeratosis of most or all of the skin. "The patient's presentation of ichthyosis is supported by a heterozygous variant of uncertain significance (VUS) in the ABCA12 gene (c.5779‐1G>A)." (PMID 41550404, 2026). "The WES results revealed compound heterozygous variations in gene ABCA12, inherited from the fetus's parents, which is associated with congenital ichthyosis." (PMID 39748812, 2024). "Genetic analysis of patients with ichthyosis revealed 64 families with mutations in ABCA12 in our laboratories." (PMID 36980989, 2023). "Target NGS of 27 genes associated to congenital ichthyosis was performed, and identified the compound heterozygous mutations c.233_234del (p.Thr78ArgfsTer3) and c.1287 + 2_1287 + 5del of the ABCA12 gene." (PMID 35964051, 2022). "Mutation of ABCA12 leads to defects in lipid transport and dysfunction of the skin barrier, leading to congenital ichthyosis." (PMID 35783291, 2022). "A loss-of-function mutation in ABCA12 impairs lipid lamellar membrane formation in the SC, causing harlequin ichthyosis, which is the most severe phenotype of autosomal recessive congenital ichthyosis." (PMID 32054030, 2020). "Our findings of a novel ABCA12 missense mutation further contribute to the mutational diversity of ABCA12-related ichthyosis and will facilitate structure-function and genotype-phenotype correlations." (PMID 24278723, 2012). "Although mutations in ABCA12 are known to be associated with Ichthyosis, and many different mutations within this gene have been documented, the missense mutation detected in the two families we investigated had not previously been described." (PMID 24278723, 2012). "Here we report a novel missense mutation in exon 32 of ABCA12 (p.Gly1559Val) that is associated with the development of congenital ichthyosis in two apparently unrelated families of Pakistani origin." (PMID 24278723, 2012). "In Harlequin syndrome, characterized by disturbance in lamellar granule, ichthyosis and severe genodermatosis, ABCA12, an ATP-binding cassette transporter, is mutated." (PMID 20305790, 2010). "The main cause for HI are truncating mutations in ABCA12 (ichthyosis, congenital, autosomal recessive 4B (harlequin), and MIM #242500), whereas missense mutations in ABCA12 usually lead to milder phenotypes such as CIE or LI (ichthyosis, congenital, autosomal recessive 4A, and MIM #601277)." (PMID 36980989, 2023). "It has been suggested that the type of mutation is correlated with the ARCI phenotype: homozygotes or compound heterozygotes with truncating ABCA12 mutations lead to the harlequin ichthyosis phenotype whereas missense mutations result in the LI and CIE phenotypes." (PMID 32069299, 2020). "ABCA12 is the only gene associated with the harlequin ichthyosis phenotype." (PMID 32069299, 2020). "Despite the genetic heterogeneity of autosomal recessive congenital ichthyosis, exome resequencing and prioritisation of homozygous novel variants (in view of the consanguinity present in both families) enabled us to rapidly identify a candidate ABCA12 novel missense mutation." (PMID 24278723, 2012). "Unlike classic Joubert syndrome, this patient had profound developmental regression and ichthyosis, suggesting modifying effects from ABCA12, DOCK6, and the 14q deletion." (PMID 41550404, 2026). "Pathogenic variants in the ABCA12 gene cause various forms of autosomal recessive congenital ichthyosis (ARCI), such as severe harlequin ichthyosis (HI) and milder lamellar ichthyosis (LI) and congenital ichthyosiform erythroderma (CIE)." (PMID 39748812, 2024). "Two SNVs in the ABCA12 gene related to Ichthyosis, congenital, autosomal recessive 4B (harlequin) (OMIM #242500) were identified." (PMID 37592284, 2023).
ichthyosis (continued). "To summarize, we report three novel mutations, two of which were located in ABCA12 gene responsible for ILC, a rare clinical form of ichthyosis, as well as novel clinical characteristics associated with particular genotypes." (PMID 34983512, 2022). "After the genetic sequencing, variants were found in ABCA12 and HRNR which are related to several skin diseases, including ichthyosis." (PMID 34039366, 2021). "In this model, a moderate ichthyosis phenotype was observed, likely due to residual ABCA12 protein expression." (PMID 32544098, 2020). "To date, multiple genes have been shown to be associated with ichthyosis, including ALOXE3, ALOX12B, TGM1, CYP4F22, NIPAL4, and ABCA12." (PMID 24278723, 2012). "Here, we report a unique case of a child with neuro‐ichthyosis presenting with pharmacoresistant epilepsy, severe developmental delay, and ichthyosis, in whom whole exome sequencing revealed multilocus pathogenic variants including CC2D2A, ABCA12, DOCK6, and a 14q31.3–q32.11 deletion." (PMID 41550404, 2026). "In this context, a particular form of non-syndromic ichthyosis (ILC) with multiple localized polycyclic erythematous and squamous plaques and brownish fine scales was found in patients carrying two novel missense mutations in ABCA12 gene." (PMID 34983512, 2022). "Additionally, 15 genes involved in lipid metabolism were differentially expressed, some directly involved in ichthyosis, e.g., ABCA12, ALOX5, ALOX12B, ALOXE3, CYP4F2, and 2 elongation of very long chain fatty acid protein (ELOV) genes." (PMID 32544098, 2020). "There are 6 genes currently known to be associated with ichthyosis: ALOXE3, ALOX12B, TGM1, CYP4F22, NIPAL4, and ABCA12, and although thought to be unrelated, both the probands from family 1 and family 2 harboured an identical novel missense variant, c.G4676T, p.Gly1559Val in ABCA12." (PMID 24278723, 2012). "Prenatal diagnosis through DNA testing can identify mutations in the ABCA12 gene, and chorionic villus sampling (CVS) or amniotic fluid cell analysis can confirm the condition, especially in mothers with a history of previous children diagnosed with ichthyoses." (PMID 39882557, 2025). "Ten patients suffered from congenital ichthyosis, seven of them having lamellar ichthyosis (Ichthyn: n 4, CYP4F22: n 1, TGM1: n 1, ongoing analysis: n 1) and three cases of congenital ichthyosiform erythroderma (two patients who carried ABCA12 mutations, and one who had no identified mutation)." (PMID 29618363, 2018).